CD28 (CD28 molecule)
Diseases named in the same sentence as CD28 in open-access papers (continued):
Sharing a sentence is not in itself a finding about the gene and the disease.
tumor (continued). "However, a large fraction of the tumor-resident CD8+ T-cells have phenotypic changes, with high levels of programmed death-1 (PD-1) and Tim-3, and low levels of the immune co-receptors CD27 and CD28, losing their anti-tumor functions." (PMID 31181729, 2019). "However, in the setting of tonic CAR signaling, 4-1BB costimulation reduces exhaustion induced by persistent CAR signaling and augments anti-tumor activity in vivo, while CD28 costimulation does not." (PMID 29980239, 2018). "For analysis of cytokine release, T cells genetically engineered to express either only EGFP (vector control), UniCAR stop or UniCAR CD28/ζ were cultivated with or without tumor cells at an e:t ratio of 5:1, either in the presence or absence of 30 nM of anti-CD19 TM for 24h." (PMID 29484126, 2018). "Indeed, compared to the first generation of CAR T cells, (i) CD28-CAR T cells secrete higher levels of interferon gamma (IFNγ); (ii) efficiently eradicate transforming growth factor beta (TGFβ) producing tumor cells; and (iii) suppress TGFβ inhibition of T cell expansion." (PMID 28496440, 2017). "High levels of CD8+CD28+ T cells were occurred in patients with negative tumor markers." (PMID 28624781, 2017). "In addition, lymphocyte CTLA-4 expression, tumor CD28 expression, and lymphocyte CD28 expression were not significant prognostic factors for OS, FFS, D-FFS, or LR-FFS." (PMID 26918337, 2016). "However, such external anti-CD3/CD28 or IL-2 models are artificial and do not reflect the actual state in tumor microenvironment." (PMID 26895379, 2016). "We investigated whether T cells expressing an anti-CD19, CD3 zeta and CD28-based CAR (19-28z) displayed the same proliferation and anti-tumor abilities than T cells expressing a CD3 zeta-based CAR (19z1) costimulated through the CD80/CD28, ligand/receptor pathway." (PMID 26110267, 2015). "The expression levels of T-cell markers, such as CD28 and CD3 epsilon, were not affected by the risk haplotypes, so the expression reduction in TRPC6 and other genes involved in T-cell activation was not due to the absence of T-cells within the tumor." (PMID 25642983, 2015). "In line with this notion, our results clearly show that the combination of 2-DG and radiation elicits anti-tumor immune response by not only restoring the levels of CD4+ cells, but also the levels of molecules related to its signaling i.e. CD44, CD69, CD45, TCR-β, TCR-γδ and CD28." (PMID 25248151, 2014). "In addition, a significant down-regulation of CD28 was induced in naïve CD4+ T cells after co-culture with the different types of tumor cell lines but not with normal breast cells." (PMID 25231413, 2014). "Since CD28 costimulatory signals may not only bolster augmented T-cell function but also prevent T-cell AICD, we believe that the principles established in this study will significantly enhance anti-tumor activity of targeted BsAb-based tumor immunotherapy." (PMID 25496493, 2014). "In this regard, it is noteworthy that 4-1BB co-stimulation increased CD28 expression and critical effector molecules needed for tumor killing (Perforin, GB, Eomes) without significantly increasing KLRG-1, a marker for end-stage effector cells approaching senescence." (PMID 23560068, 2013). "It would be interesting to directly compare second generation (i.e., the CAR construct with 4-1BB plus CD3zeta chain without CD28) versus third generation CARs in our tumor model, and we have in fact undertaken such a comparative study (manuscript in preparation)." (PMID 24829757, 2013). "However, switching from the G4S to the Whitlow/218 linker in SKM-CAR-T cells with the CD28 co-stimulatory domain significantly altered cytokine expression after antigen stimulation and improved the in vitro tumor cell killing activity, but not the in vivo tumor control." (PMID 40308593, 2025).
tumor (continued). "However, despite some delay in tumor progression seen upon transfer of NKp30-CD137 CAR TCRKO T cells, we could not observe better persistence of NKp30-CD137 CAR TCRKO engineered T cells compared to CD28-costimulated CAR T lymphocytes." (PMID 40943160, 2025). "Our results showed that the co-stimulatory CD28 cytoplasmic domain could accelerate the proliferation of NECTIN-4 TAC28-T cells and enhance their cytotoxicity on target cells, and more importantly, increase the infiltration of NECTIN-4 TAC28-T cells into tumor lesions." (PMID 39735536, 2024). "Based on immunophenotyping tumours, we speculate that this differential effect may, in part, be attributed to the capacity of anti-CTLA-4 blocking the CTLA-4 immunosuppressive properties such as attenuation of CD28 signalling through binding of CD80/8635,52,53." (PMID 39322643, 2024). "However, interestingly, even in the absence of external activation from tumor cells, T cells can activate CD28 costimulatory signals by cis-B7:CD28 interactions at invaginated synapticmembranes, that is autologous signaling, thereby enhancing their ability to attack tumors." (PMID 38816871, 2024). "Third, γδ T cells persist longer than CD28-costimulated CAR T cells, as was shown in a recent clinical trial, and have been found years after adoptive transfer in CD19 CAR T cell-treated patients, which could be relevant for persistent activity against tumor recurrence." (PMID 38541651, 2024). "Collectively these data indicate that, although overall CD8+ PD1+ T cells may encounter unfavorable conditions in the tumor microenvironment, a significant functional response may still occur, likely regulated by distinctive mechanisms depending on the presence/absence of CD28." (PMID 37898752, 2023). "However, given the absence of lymphocyte stimulators and the state of the tumor, conditioning PBLs with IL-2 and CD28 may further augment the cytotoxic potential of T cells with anti-PDL1-BiTE." (PMID 39282109, 2023). "Similarly, addition of anti–CD28 agonist Ab did not modulate tumor cell recognition." (PMID 36512410, 2023). "Finally, in the tumor we observed a significant functional decline of PD1+ T cells lacking both CD28 and the other four IRs (C IR-1), suggesting that in the tumor site, in the absence of CD28, additional mechanisms rather than IR expression restrain T-cell functionality." (PMID 37898752, 2023). "To highlight this different CD137 and ICOS related scenario found in the tumor with respect to the periphery, when CD28 is lacking, we cannot rule out that a fraction of intra-tumor PD1+CD28− T cells may have switched to a Treg-like phenotype, likely driven by the local milieu." (PMID 37898752, 2023). "Notably, the dual CAR-T cells transduced with both CD19 scFv-CD28-CD3z and PSMA scFv-PD-1-intracellular trail could be inactivated by PSMA, suggesting that this concept might be feasible for optimizing the on-target, off-tumor effect of CAR." (PMID 34830003, 2021). "In addition, complete T cell activation requires the co-stimulation of the B7 molecule on APCs and the CD28 molecule receptor on T cells, while HCC downregulates the expression of co-stimulatory molecular receptors such as B7.1/B7.2, leading to the escape of tumor immunity." (PMID 34745958, 2021). "Importantly, the CD27+CD28+ phenotype was more frequently—though variable for each patient with NSCLC—observed in tilTemra, and its presence was largely dependent on a persistent low-grade TCR signal, implying a close relationship with the immunogenicity of tumor antigens." (PMID 34593620, 2021). "Thus, treating patients prior to surgery with anti-PD1 antibody with or without 4-1BB agonism, followed by adjuvant CAR T cells with a third generation CD28/4-1BB-based CAR construct, could take advantage of the less “cold” tumour microenvironment to eliminate and control peripheral disease." (PMID 34638471, 2021).
tumor (continued). "However, its expression on other cell populations, such as tumor or NK cells lacking CD28, suggests that it could have other unrevealed roles on different cell populations." (PMID 32781690, 2020). "However, its expression on other cell populations, such as tumor or NK cells lacking CD28, suggests that it could have other unexpected roles." (PMID 32024070, 2020). "In addition, localized or targeted use of anti-CD28 mAbs has much potential such as incorporating the intracellular costimulatory domain of CD28 into CAR (chimeric antigen receptor) T cells for adoptive transfer immunotherapy and the use of CD28 agonist aptamer with tumor vaccine." (PMID 31181772, 2019). "Thus, under the same anti-CD3 and anti-CD28 stimulation system, three subpopulations of CD8+ T cells were sorted by Aria II (BD) with purity > 90% and co-cultured in U-bottom plate with HCCLM3 HCC tumor cell line pre-labeled with CFSE according to the manufacture’s instruction." (PMID 31783783, 2019). "To determine whether Kindlin-3 expression may reflect the amount of tumor infiltrating leukocytes (TILs) we analyzed the mRNA levels of different immune markers in the same series of tumors and found that triple negative and ERBB2 tumors presented the highest levels of CD45, CD86, CD28 and CD4." (PMID 30477537, 2018). "However, whether CD28 expression on TILs or tumor cells influences the prognosis of NPC patients has not been evaluated." (PMID 26918337, 2016). "These conditioned macrophages were then co-cultured with autologous non-adherent PBMCs and tumor cells in the presence of IL-2 and α-CD3/CD28 stimulation to activate T cells." (PMID 41488634, 2025). "Ideally, tumor antigens selected for CD3 and CD28 TCE combinations should have non-overlapping expression patterns in healthy tissues, increasing tumor specificity and minimizing OTOT toxicity of the combination immunotherapy to maximize the therapeutic index." (PMID 39301613, 2025). "Second, we have not compared the TIL’s expansion yield, anti-tumor efficacy, clones’ diversities, exhaustion status by using T cell activator CD3/CD28 beads vs. anti-CD137 agonist antibody protocol." (PMID 40145091, 2025). "Strikingly, we found that ATP at concentrations found in tumor and infectious environments inhibits anti-CD3/CD28–stimulated CD4+ T cells from noninfected control mice." (PMID 40590226, 2025). "Most tumor-infiltrating CD8 + T cells are in the early effector memory stage of differentiation, co-expressing CD27, CD28, CD57, and Granzyme B, with little or no perforin." (PMID 39105866, 2024). "Splenocytes were cultured directly with infected or non-infected tumours for 24 h, and levels of Lck phosphorylation were detected by flow cytometry after 15 min α-CD3/α-CD28 stimulation." (PMID 39558103, 2024). "We found that PD-1 ablation enhanced the anti-tumor efficacy of LA but not HA HER2 CAR-T cells in mice containing SKOV3 wild-type tumors, consistent with our earlier findings in CD28-based CAR-T cells." (PMID 38670972, 2024). "To further investigate the mechanism of immunosuppression by Sema6D, we isolated T cells from tumor-draining LNs and stimulated them with anti-CD3/anti-CD28 antibodies with or without rSema6D." (PMID 38329122, 2024). "Of note, in the tumor site also CD137 and ICOS failed to provide functional advantage to CD28- T cells, nevertheless still sustained by CD11ahigh, although expressed only in a small fraction of the subset." (PMID 37898752, 2023). "We characterized the anti-tumor cytokine response of tumor-bearing and non-tumor-bearing mice after ex vivo restimulation with CD3/CD28 antibodies or IR HNSCC tumor antigen preparations in these models." (PMID 37444444, 2023). "Our results indicate that tumor cells exposed to IR are capable of inducing T cell immune responses, which, although not as robust as CD3/CD28 stimulation, can potentially serve as an indicator of antitumor immune responses in HNSCC." (PMID 37444444, 2023).
tumor (continued). "Upon anti-PD1 treatment, no CD8 + /CD28 + T cells were noted in PNI patients with a high NII score,and tumor cells(CK marked) were still diffused in the TME." (PMID 37563649, 2023). "The carefully regulated dual CD28/CTLA-4 mechanisms ensure that the anti-pathogen and anti-tumor immune effects are carried out without autoimmune responses and collateral damage to normal tissues." (PMID 37110545, 2023). "We, therefore, used both models to analyze cytokine responses after the stimulation of tumor-bearing and non-tumor-bearing lymph node cells with the IR-generated HNSCC tumor antigen or CD3/CD28 antibodies." (PMID 37444444, 2023). "With a CAR consisting of a HER-2-targeting scFv and a chimeric CD28-TCRζ signaling domain, CAR-NK cell responses to tumor cells did not correlate with HLA-I expression." (PMID 35585985, 2022). "Binding of CD28 family receptors such as CD28, CTLA-4, PD-1 and ICOS on active T cells with B7 family ligands on antigen presenting cells and tumor cells triggers negative signal transduction for T cells, resulting in attenuated cell activation and growth." (PMID 35402280, 2022). "To exclude tumor-induced transcriptomic changes, we used anti-CD3/CD28-bead-based activation in the presence or absence of SB-431542 or rTGF-β." (PMID 35454831, 2022). "Although PD-1 and TIGIT are thought to regulate different costimulatory receptors (CD28 and CD226), effectiveness of PD-1 or TIGIT inhibition in preclinical tumor models was reduced in the absence of CD226." (PMID 35263569, 2022). "To exclude that simple CAR binding to cell surface GRP78 contributes to tumor cell killing, we designed a non-functional GRP78.1x-CAR (GRP78.ΔCAR) that lacked the CD28 costimulation and CD3ζ activation domains but was otherwise identical to the GRP78.1x-CAR." (PMID 35102167, 2022). "While CD80 has been considered to be a leading costimulator for T cells through CD28, to our surprise, CD80 costimulation did not improve tumor control." (PMID 36073543, 2022). "In fact, tumour infiltrating CD8+ T cells are TCF1 negative and CD28 negative and do not respond to PD-1 blockade." (PMID 33802622, 2021). "In a different study, PSMA × CD28 and EGFR × CD28 BsAbs enhanced the antitumor efficacy of the PD-1 blockade in syngeneic and xenograft tumor models and did not induce systemic T cell activation." (PMID 34358141, 2021). "We performed the same in vivo experiments with the only difference being that this time, CAR T cells expressed ffLuc (NT.ffLuc, CD28.z.ffLuc, 41BB.z.ffLuc) and not the JIMT-1 tumor cells." (PMID 34503109, 2021). "CD8+ T cells were purified from HLA-A2 restricted individuals, including NC (peripheral bloods, n = 6) and GC patients (peripheral bloods and tumor tissues, n = 17), and were stimulated with or without Pam3Csk4 for 12 h in the presence of anti-CD3/CD28." (PMID 34620075, 2021). "In order to interrogate the performance of CD28-, 41BB-, and MC-CAR T cells upon chronic antigen exposure, we repeatedly exposed them to fresh tumor cells in the absence of exogenous cytokines until they stopped killing." (PMID 33148882, 2020). "Collectively, we found that PD-1, CTLA-4, VISTA, CD28, OX-40, 4-1BB, ICOS, and GITR were significantly increased in tumor tissues compared with non-tumor tissues." (PMID 33552954, 2020). "The percentages of CD28 negative cells were lower between CD4+ (but not CD8+) T cells from spleens and LN of fully recovered mice compared to tumor-free mice." (PMID 31717542, 2019). "Most evaluations have centered primarily on the role of CD8+T cells in peripheral blood and the tumor microenvironment in various tumors, with no further classification of CD28 cells into CD28+ and CD28− subgroups." (PMID 31623615, 2019). "In all our cases, lymphocytes intermingled between tumor cells and in tumor stroma were deactivated (negative for activation markers CD25, CD28, CXCR3, CCR6), thus not attacking tumor cells." (PMID 29520483, 2018).
tumor (continued). "Younger patients, females and those with negative tumor markers presented increase of CD4+, CD8+CD28+ T cells, and CD4/CD8 ratios in the periphery, which is consistent with a previous study." (PMID 28624781, 2017). "Aside CTLA-4 expression, there were no clear differences in the expression of CD28, CD45RO, and CD62L between PD-1+ cells in tumor infiltrating CTLs at the tumor site and whole CD8+ T cells." (PMID 29163789, 2017). "Next, we investigated the specificity of the anti-CD19 CARs, focusing on anti-CD19/CD28 CAR against both CD19 positive and negative tumor cells." (PMID 27598655, 2016). "In contrast, the preoperative serum levels of CTLA‐4, B7‐H3, CD28, CD80, and CD86 were not correlated with tumor biological characteristics in this study." (PMID 27292320, 2016). "In contrast, r28M as well as CD3 and CD28 alone, did not lead to IL-2 secretion and thus to no activation of PBMC in the absence of tumor cells." (PMID 26469402, 2015). "Co-stimulatory signals, such as those mediated by CD28, OX40 (a tumour necrosis factor receptor) and CD40L, enable a more efficient and long-lasting activation of T cells, but often tumours do not express appropriate ligands for such co-stimulatory molecules." (PMID 26035842, 2015). "Although the percentage of proliferating cells in spleens were lower in all treated mice, as compared with tumour/bearing untreated mice, the capacity of the CD8+ spleen cells to proliferate upon CD3/CD28 activation was not significantly impaired." (PMID 22015556, 2011). "To test whether Treg expansion occurs independently of tumor antigens, we stimulated T cells ex vivo in lymph node cultures from naïve mice using anti-CD3/CD28, with or without auranofin." (PMID 41300507, 2025). "Notably, after in-vitro expansion in the presence of exogenous TGFβ (6 days), a considerable CXCL13 production was found only in cells from the tumor, mainly characterized by a PD1+CD28− TRM phenotype, and not in NT tissue." (PMID 37898752, 2023). "Differently, differences between the two subsets were clearly less evident at the NT and even not significant in the tumor site, either in terms of IFN-ɣ, TNF-α and polyfunctionality, with a partial functional advantage of PD1+CD28− T cells only in terms of GrzB (P < 0.003)." (PMID 37898752, 2023). "Finally, although not significant, in progression-free subjects—CD8+ CD28+ PD-1+ T cells were in closer proximity to both APCs (CD11c+ CD86+) and tumor cells (CK+) especially in the tumor-surrounding stroma, compared to PD." (PMID 37349318, 2023). "Focusing on NSCLC, then we evaluated the dynamic distribution and functionality of PD1+CD28− and PD1+CD28+ T-cell subsets in 68 treatment-naïve NSCLC patients, by comparing peripheral blood, adjacent non-tumor (NT) tissue and tumor site (T) (n = 32 matched NSCLC patients)." (PMID 37898752, 2023). "The comparison of constructs, including 4-1BB or CD28 costimulatory domains, showed that 4-1BB-based constructs, unlike CD28-based ones, could control the new CD33+ THP1 tumor cells added to the medium after 7 days." (PMID 36761751, 2023). "However, when targeting tumor cells with low antigen density, 4-1BB-based CAR T cells sometimes fail to be activated, whereas this is not the case of CD28-based CAR T cells." (PMID 36389701, 2022). "In contrast, the control RNA NPs without CD28 aptamer could not bridge CD8+ T cells and tumor cells in either PSMA+ LNCap or PSMA− PC3 cells." (PMID 33868786, 2021). "Tumor‐free induction by ETSB could be evidently terminated by αβTCR, CD28, single Vγ4TCR, or Vγ4/1TCR elimination, yet not by single Vγ1TCR depletion." (PMID 31832307, 2019). "Thus, the CD19-driven CD28 signal given in the absence of CD80 molecules is sufficient to trigger T-cell sustained proliferation and anti-tumor activity, which are unaffected by CTLA-4 inhibition." (PMID 26110267, 2015).